ETHE1 (ETHE1 persulfide dioxygenase)
Description:
Sulfur dioxygenase that plays an essential role in hydrogen sulfide catabolism in the mitochondrial matrix. Hydrogen sulfide (H(2)S) is first oxidized by SQRDL, giving rise to cysteine persulfide residues. ETHE1 consumes molecular oxygen to catalyze the oxidation of the persulfide, once it has been transferred to a thiophilic acceptor, such as glutathione (R-SSH). Plays an important role in metabolic homeostasis in mitochondria by metabolizing hydrogen sulfide and preventing the accumulation of supraphysiological H(2)S levels that have toxic effects, due to the inhibition of cytochrome c oxidase.
Synonyms: HSCO; YF13H12
Tractability: PROTAC: ubiquitination databases record sites on it; its protein half-life has been measured.
Gene: Protein-coding gene on chromosome 19 (43,506,719 to 43,527,257, reverse strand). Ensembl gene ENSG00000105755.
Subcellular location: Cytoplasm; Nucleus; Mitochondrion matrix
Subcellular location (Human Protein Atlas): Mitochondria
Pathways (Reactome):
Metabolism: Sulfide oxidation to sulfate
Gene Ontology:
Molecular function: identical protein binding; iron ion binding; protein binding; sulfur dioxygenase activity
Biological process: glutathione metabolic process; sulfide oxidation; hydrogen sulfide metabolic process
Cellular component: cytoplasm; mitochondrial matrix; mitochondrion; nucleus
Genetic constraint (gnomAD): Loss-of-function variants: 16 observed, 25.05 expected, observed/expected ratio (o/e) 0.64, 90% interval 0.43 to 0.97. The upper end of that interval is the gene's LOEUF score, 0.97, which puts it in group 4 of 6, group 1 being the genes least tolerant of losing a copy. Missense variants: 300 observed, 329.2 expected, observed/expected ratio (o/e) 0.91, 90% interval 0.83 to 1. Synonymous variants: 139 observed, 132.05 expected, observed/expected ratio (o/e) 1.05, 90% interval 0.92 to 1.21.
Gene-disease validity (ClinGen):
ClinGen rates the evidence that ETHE1 causes each of these diseases.
Leigh syndrome (autosomal recessive): Definitive. A progressive neurological disease defined by specific neuropathological features associating brainstem and basal ganglia lesions.
Homologues: Orthologues: macaque ETHE1 (97% identical), mouse Ethe1 (90% identical), chimpanzee ETHE1 (89% identical), rat Ethe1 (88% identical), guinea pig ETHE1 (84% identical), pig ETHE1 (80% identical), tropical clawed frog ethe1 (64% identical), zebrafish ethe1 (62% identical), Drosophila melanogaster CG30022 (56% identical), Caenorhabditis elegans ethe-1 (48% identical). Paralogues in human: HAGHL (26% identical), PNKD (25% identical), HAGH (24% identical), MBLAC2 (18% identical).
Diseases named in the same sentence as ETHE1 in open-access papers:
ETHE1 is named in the same sentence as 34 diseases in open-access papers, as found by Europe PMC text mining. Sharing a sentence is not in itself a finding about the gene and the disease. The quoted sentences say what the papers report.
ethylmalonic encephalopathy (41 papers, 2009 to 2025). "Ethe1 was first reported in ethylmalonic encephalopathy, where mutations in this gene lead to metabolic disorders in the gastrointestinal tract and peripheral blood vessels." (PMID 40520024, 2025). "Previous studies showed that strategies to decrease H2S production were beneficial in patients with ethylmalonic encephalopathy, a subtype of Leigh syndrome that is caused by ETHE1 deficiency." (PMID 38870029, 2024). "Loss of or mutations in ETHE1 leads to ethylmalonic encephalopathy in humans, characterized by brain damage, lactic acidemia, and even death." (PMID 37834012, 2023). "We discuss the gene therapy approaches available for ethylmalonic encephalopathy caused by mutations on ETHE1 as an emblematic example of mitochondrial encephalopathy caused by the toxic accumulation of sulfide." (PMID 35745859, 2022). "Mutation of ETHE1 prevents efficient clearance of hydrogen sulfide from tissues, indirectly impairing mitochondrial respiration and manifesting as ethylmalonic encephalopathy (EE, MIM #602473)." (PMID 36475414, 2022). "Recessive mutations in ETHE1 lead to ethylmalonic encephalopathy (EE), a fatal mitochondrial disease characterized by the accumulation of hydrogen sulfide (H2S) and ethylmalonic acid (EMA)." (PMID 35745859, 2022). "This study investigated H2S concentration in plasma and urine of patients with diagnosed ethylmalonic encephalopathy, as well as the phenotype of an animal model of ETHE1 deficiency." (PMID 34356298, 2021). "Kabil and Banerjee reported on two different mutations in persulfide dioxygenase (ETHE1), which causes ethylmalonic encephalopathy in humans." (PMID 34356298, 2021). "Another disease that directly affects cellular cysteine catabolism is ethylmalonic encephalopathy or ETHE1 deficiency." (PMID 33271457, 2021). "This is the case of the ethylmalonic encephalopathy caused by mutations in the ETHE1 gene encoding for a mitochondrial sulfur dioxygenase involved in the detoxification pathway of hydrogen sulfide (H2S)." (PMID 33187380, 2020). "Among the group of mitochondrial disorders, there is another disease of sulfur metabolism, called ethylmalonic encephalopathy or ETHE1 deficiency." (PMID 33488670, 2020). "Treated Ethe1-deficient mice had a prolonged lifespan, and five ethylmalonic encephalopathy patients demonstrated marked clinical improvement following combined therapy." (PMID 28467362, 2017). "NAC has also been used in combination with metronidazole to treat ethylmalonic encephalopathy, a disorder caused by mutations in ETHE1 that result in secondary inhibition of cytochrome c oxidase and other enzymes." (PMID 28467362, 2017). "Studies32, 33, 34 have shown that a defect in the ETHE1 gene can induce a severe mitochondrial disease (ethylmalonic encephalopathy), causing energy metabolism disorders in cells." (PMID 27966587, 2016). "Mutations in ETHE1 causing loss of function result in sulfide toxicity and in the rare fatal disease Ethylmalonic Encephalopathy (EE)." (PMID 25198162, 2014). "Ethylmalonic encephalopathy (EE) is an autosomal recessive deletion in the ETHE1 gene that encodes a mitochondrial sulfur dioxygenase." (PMID 23355823, 2013). "COX activity is reduced in muscle, brain, and colon of individuals with ethylmalonic encephalopathy which is caused by mutations in the ETHE1, and in muscle, brain, and liver of Ethe1−/− mice." (PMID 23028699, 2012). "Interestingly, thiosulfate also accumulates in ethylmalonic encephalopathy (EE) caused by defects in the enzyme persulfide dioxygenase encoded by the ETHE1 gene." (PMID 41178722, 2025).
ethylmalonic encephalopathy (continued). "Increasing evidence has suggested that ETHE1 is involved in the metabolism of cellular hydrogen sulfide, and mutations in ETHE1 can lead to dysregulation of the physiological process, resulting in ethylmalonic encephalopathy." (PMID 37834012, 2023). "Despite its pivotal role in ethylmalonic encephalopathy, whether dysregulation of ETHE1 is implicated in human cancer is poorly understood." (PMID 37834012, 2023). "LT also resulted in an effective option to treat ethylmalonic encephalopathy due to mutation in ETHE1 gene, since the replaced organ can substitute the deficient ETHE1 enzyme and clear the toxic H2S that accumulate in this disorder, constituting a feasible therapeutic option in patients." (PMID 33187380, 2020). "Previous studies have shown that germline ETHE1 mutations in ethylmalonic encephalopathy lead to an accumulation of H2S and inhibition of Cytochrome C Oxidase (COX) which is essential for mitochondrial respiration, affecting severe dysfunction in cellular energy metabolism." (PMID 31258845, 2019). "Moreover, accumulation of hydrogen sulfide due to mutations in ETHE1 has been associated with cytochrome oxidase (COX) deficiency in ethylmalonic encephalopathy." (PMID 27856619, 2017). "Ethylmalonic encephalopathy classically has heterogeneous phenotypes with neurological, gastrointestinal, metabolic and psychiatric sequelae and results from mutations in the ETHE1 gene." (PMID 27190030, 2016). "It is also known that defects in ETHE1 are a cause of ethylmalonic encephalopathy." (PMID 21073729, 2010). "Ethylmalonic encephalopathy (EE) is an autosomal recessive mitochondrial disease caused by a mutation in the ethylmalonic encephalopathy protein 1 (ETHE1) gene." (PMID 35668433, 2022). "For instance, accumulation of hydrogen sulfide in patients with ethylmalonic encephalopathy (a disease caused by mutations in the ethylmalonic encephalopathy protein 1 (ETHE1) gene coding for a sulfur dioxygenase) may be reduced by the combined application of N-acetylcysteine and metronidazole." (PMID 36614050, 2022). "In 2004, for the first time, recessive variants of ETHE1 (ethylmalonic encephalopathy protein 1) were identified as the causes of EE." (PMID 32362910, 2020). "EE is caused by mutations to the gene (HGNC: 23287) encoding for the ethylmalonic encephalopathy protein 1 (ETHE1, also known as sulphur dioxygenase, SDO) and correlates with increased cellular levels of hydrogen sulfide." (PMID 25596185, 2015). "Genetic lesions in the ETHE1 gene are associated to ethylmalonic encephalopathy (EE), a devastating infantile metabolic disorder affecting the brain, gastrointestinal tract, and peripheral vessels." (PMID 25198162, 2014). "Mutations that lead to a loss of function in ETHE1 disrupt mitochondrial sulfide oxidation and thereby cause the fatal metabolic disorder, EE (ethylmalonic encephalopathy; OMIM #602473)." (PMID 23800285, 2013). "SDO in humans was initially recognized as ETHE1 protein (ethylmalonic encephalopathy 1) since it was recognized that ETHE1 gene mutation leads to ethylmalonic encephalopathy (EE)." (PMID 24312599, 2013). "It has been well documented that ETHE1 is the key gene responsible for a rare autosomal dominant inherited metabolic disease, which is termed Ethylmalonic Encephalopathy." (PMID 39198402, 2024). "ETHE1 has been extensively explored in ethylmalonic encephalopathy, but its investigation in CRC is limited." (PMID 39198402, 2024). "Excessive accumulation of H2S can increase levels of C4 and C5 acylcarnitines and thiosulfate, changes that have been observed in a mouse model of ethylmalonic encephalopathy (ETHE1-knockout mice)." (PMID 38870029, 2024). "Dysregulation of ETHE1 leads to ethylmalonic encephalopathy in humans; however, the role of ETHE1 in TNBC remains elusive." (PMID 37834012, 2023). "Although ETHE1 plays a key role in ethylmalonic encephalopathy, its role in human cancer is poorly understood." (PMID 37834012, 2023).
ethylmalonic encephalopathy (continued). "Ethylmalonic encephalopathy (EE; OMIM #602473) is a fatal, early onset, autosomal recessive mitochondrial disease caused by mutations in ETHE1." (PMID 22903887, 2012). "The detected proteins are involved in a wide range of diseases; spastic paraplegia (HSPD1), cancer (BAX, PHB), optic atrophy (OPA1), ethylmalonic encephalopathy (ETHE1) and Parkinson's disease (NDUFV2)." (PMID 19476632, 2009). "Similarly, ethylmalonic encephalopathy (EE; OMIM #602473), an autosomal recessive mitochondrial disease associated with progressive neurological failure, is caused by mutations in ETHE1." (PMID 31657521, 2019). "AAV-mediated hepatic ETHE1 gene expression restores sulphur dioxygenase activity in a murine model of ethylmalonic encephalopathy, correcting biochemical abnormalities within liver, muscle, and brain; and increasing survival from a few weeks to more than 6 months." (PMID 27190030, 2016). "Here, we will review two peculiar mitochondrial disorders, ethylmalonic encephalopathy (EE) and mitochondrial neurogastrointestinal encephalomyopathy (MNGIE), caused by mutations in the ETHE1 and TYMP nuclear genes, respectively." (PMID 26194912, 2015). "In patients suffering from EE (ethylmalonic encephalopathy), a block in sulfide oxidation at the level of the SDO (sulfur dioxygenase) ETHE1 leads to severe dysfunctions in microcirculation and cellular energy metabolism." (PMID 23800285, 2013). "For example, mutations that affect the activity of mitochondrial persulfide dioxygenase (ETHE1, the enzyme in charge of GSSH degradation) are responsible for ethylmalonic encephalopathy, an inborn error of metabolism that leads to neurodevelopmental complications." (PMID 36213129, 2022). "The ETHE1 (ethylmalonic encephalopathy 1) gene in humans was identified as the SDO gene, and its dysfunction can lead to a fatal autosomal recessive mitochondrial disease: ethylmalonic encephalopathy." (PMID 30809466, 2019).
colorectal cancer (6 papers, 2019 to 2024). A primary or metastatic malignant neoplasm that affects the colon or rectum. "A recent study showed that ETHE1 is overexpressed in colorectal cancer, promoting aerobic glycolysis and mitochondria biogenesis." (PMID 38283944, 2023). "To date, only a few studies have indicated the role of ETHE1 in tumorigenesis of colorectal cancer." (PMID 37834012, 2023). "We suggested for the first time that downregulation of mitochondrial genes, including ETHE1, SQOR, TST, and GPX3, would help colorectal cancer cells to produce more energy under hypoxic conditions through mechanisms that are different from “Warburg Effect”." (PMID 34249670, 2021).
hepatocellular carcinoma (4 papers, 2010 to 2024). A malignant tumor that arises from hepatocytes. "In hepatocellular carcinoma (HCC), ETHE1 is overexpressed, where it is associated with inhibition of caspase 9 activation, suppressing DNA-damage induced apoptosis by binding to the RelA p65 subunit of NFkB, and increasing its export from the nucleus." (PMID 31258845, 2019).
lung carcinoma (4 papers, 2022 to 2025).
Encephalopathy (2 papers, 2013 to 2023). Encephalopathy is a term that means brain disease, damage, or malfunction. "EE patients and Ethe1-deficient mice show severe defects in motor activity and rapidly progressive encephalopathy, both of which are not fully understood yet." (PMID 23800285, 2013).
Alzheimer disease (1 paper, 2022). A progressive, neurodegenerative disease characterized by loss of function and death of nerve cells in several areas of the brain leading to loss of cognitive function such as memory and language. "This “Alzheimer’s disease” pathway overlaps with other AV-1451-associated pathways that relate to mitochondrial respiration, electron transport, and oxidative phosphorylation (NDUFS4 & 8, NDUFA6 &7, UQCRQ, & COX17), as well as metabolism (NDUFS4 & 8, NDUFA6 &7, UQCRQ, COX17, & ETHE1)." (PMID 35774552, 2022).
atherosclerosis (1 paper, 2017). A disease characterized by the build-up of fatty material and calcium deposition in the arterial wall resulting in partial or complete occlusion of the arterial lumen. "Would this further predisposes animals to atherosclerosis, and would similar effects be found with the overexpression of SQR and ETHE1?" (PMID 27844098, 2017).
breast carcinoma (1 paper, 2023). "Based on the genomic information for ETHE1 in breast cancer, we found that ETHE1 copy number was significantly elevated and closely correlated with its mRNA levels." (PMID 37834012, 2023). "Moreover, analysis of a breast cancer transcriptome dataset from the Kaplan–Meier plotter database revealed that patients with ETHE1 overexpression had worse recurrence-free survival and distant metastasis-free survival statuses." (PMID 37834012, 2023). "Therefore, we hypothesized that variations in the copy number of ETHE1 lead to its high expression in breast cancer tissues and boost TNBC metastasis." (PMID 37834012, 2023).
colitis (1 paper, 2022). Inflammation of the colon. "Studies on the other enzymes, namely ETHE1, TST and SQOR, all show a lower expression in human and in animal colitis samples." (PMID 36421421, 2022).
colon cancer (1 paper, 2024). "This study provides novel insights into the mechanisms of colon cancer angiogenesis and identifies ETHE1 as a potential therapeutic target." (PMID 39198402, 2024).
colonic adenocarcinoma (1 paper, 2024). "Consistent with our findings, a distinct meta-analysis revealed that downregulation of ETHE1 in colonic adenocarcinoma could enhance energy production under hypoxia conditions." (PMID 39198402, 2024).
cutaneous sarcoidosis (1 paper, 2024).
Ehlers-Danlos syndrome (1 paper, 2012). The Ehlers–Danlos syndromes (EDS) are a clinically and genetically heterogeneous group of heritable connective tissue disorders (HCTDs) characterized by joint hypermobility, skin hyperextensibility, and tissue fragility. "Dysregulation of H2S production is connected to connective tissue disorder in individuals with impaired collagen and elastin synthesis (e.g., Ehlers-Danlos syndrome) and patients with a deficiency of mitochondrial sulfur dioxygenase (ETHE1)." (PMID 23028699, 2012).
Familial adenomatous polyposis (1 paper, 2019). Familial adenomatous polyposis (FAP) is characterized by the development of hundreds to thousands of adenomas in the rectum and colon during the second decade of life. "We previously demonstrated a significant increase of ETHE1 expression in "single-hit" colon epithelial cells from crypts of patients with Familial Adenomatous Polyposis (FAP)." (PMID 31258845, 2019).
sarcoidosis (1 paper, 2024). Sarcoidosis is a multisystemic disorder of unknown cause characterized by the formation of immune granulomas in involved organs.
Stroke (1 paper, 2018). Sudden impairment of blood flow to a part of the brain due to occlusion or rupture of an artery to the brain. "However, the expression pattern of ETHE1 did not support a role in stroke susceptibility because the expression of Ethe1 was significantly greater (not lower) in strains with a higher risk for stroke (i.e., SHRSP and SHRpch1_18)." (PMID 29925869, 2018).
viral infection (1 paper, 2021).